DOT1L (DOT1 like histone lysine methyltransferase)
Diseases named in the same sentence as DOT1L in open-access papers (continued):
Sharing a sentence is not in itself a finding about the gene and the disease.
ovarian carcinoma (23 papers, 2017 to 2025). A malignant neoplasm originating from the surface ovarian epithelium. "Actually, mutations of the mammalian H3K79 methyltransferase DOT1L are recurrently found in several types of solid cancers, such as melanoma, colorectal cancer and ovarian cancer." (PMID 37957109, 2024). "In ovarian cancer, DOT1L has been shown to promote tumor growth by associating with estrogen receptor alpha to regulate cell cycle progression, epithelial–mesenchymal transition, drug metabolism, and cell-to-cell signaling [18,19,]." (PMID 34253709, 2021). "Collectively, those results indicated that DOT1L is overexpressed in ovarian cancer and that its overexpression is associated with poor prognosis." (PMID 34253709, 2021). "Given the fact that DOT1L has strong correlation with malignant behavior of ovarian cancer, such as late FIGO stage and poor histologic grade, a loss-of-function approach was applied to explore the function of DOT1L." (PMID 28114995, 2017). "In this study, we show that DOT1L is overexpressed in ovarian cancer and that this overexpression is linked to advanced tumor stage as patients with higher DOT1L expression exhibit shorter progression-free and overall survival (OS) than those with lower DOT1L expression." (PMID 34253709, 2021). "To understand the role of DOT1L in ovarian cancer, we first asked if DOT1L expression is altered in ovarian cancer, and if so, whether its expression is associated with disease outcomes." (PMID 34253709, 2021). "To clarify the potential prognostic roles of DOT1L in OC development and progression, we evaluated the association of DOT1L expression with various clinical features of 235 cases of OC, including 7 borderline ovarian tumors and 228 malignant ovarian tumors." (PMID 28114995, 2017). "Increased expression of DOT1L is a prognostic factor in ovarian cancer, where DOT1L promotes cancer cell proliferation and drug resistance." (PMID 41299712, 2025). "Taken together, these findings suggest that menin, at least in part through cooperation with DOT1L, promotes ovarian cancer growth through the regulation of genes involved in multiple key cellular pathways that regulate cell proliferation and survival." (PMID 39336822, 2024). "The correlation of DOT1L expression and clinicopathological parameters in ovarian cancer tissues also revealed a significant correlation between DOT1L and poor prognosis in OC." (PMID 38778348, 2024). "One such co-activator of established repute in the case of breast cancer is histone methyltransferase DOT1L, which has been suggested to be of prognostic value in ovarian cancer also." (PMID 35873467, 2022). "We show that the histone H3K79 methyltransferase disruptor of telomeric silencing 1-like (DOT1L) is overexpressed in ovarian cancer and that a higher level of DOT1L expression correlates with shorter progression-free and overall survival (OS)." (PMID 34253709, 2021). "We found that pharmacological inhibition of DOT1L upregulates the expression of the NKG2D ligand ULBP1 in a subset of ovarian cancer cells, leading to NK cell-mediated killing of the ovarian cancer cells." (PMID 34253709, 2021). "We also demonstrate that both pharmacological and genetic inhibition of DOT1L attenuates ovarian cancer growth in cell culture and in a mouse xenograft model." (PMID 34253709, 2021). "We expressed DOT1L shRNA in ovarian cancer cells to confirm our results with EPZ-5676, EPZ004777, and SGC0946 treatment." (PMID 34253709, 2021). "Collectively, our metabolomic analysis confirmed that DOT1L inhibition negatively regulates several genes involved in cellular biosynthesis, thereby decreasing the level of several metabolites in ovarian cancer cells." (PMID 34253709, 2021). "Mechanistically, DOT1L inhibition in ovarian cancer cells results in the downregulation of genes involved in cellular biosynthetic pathways and the upregulation of proapoptotic genes." (PMID 34253709, 2021).
ovarian carcinoma (continued). "In order to ascertain the specificity of the growth inhibitory effects of EPZ-5676 in the ovarian cancer cells, we also examined the effects of two other DOT1L-specific inhibitors, EPZ004777 and SGC0946." (PMID 34253709, 2021). "DOT1L is a chromatin modifier that functions by acting as an H3K79me2 transferase, which we show is overexpressed in ovarian cancer, and its overexpression is predictive of poor prognosis." (PMID 34253709, 2021). "Analysis of publicly available ovarian cancer datasets revealed that DOT1L mRNA was significantly higher in patient-derived samples of ovarian cancer than in corresponding normal tissues." (PMID 34253709, 2021). "We next performed experiments to determine the mechanism by which DOT1L inhibition attenuates ovarian cancer cell growth." (PMID 34253709, 2021). "Collectively, these results demonstrate that DOT1L inhibition effectively attenuates the growth of ovarian cancer cells, suggesting that DOT1L pharmacological inhibition can be employed for the treatment of ovarian cancer." (PMID 34253709, 2021). "Together, our results indicated that in a subset of ovarian cancer cell lines, DOT1L represses the expression of the activating NK cell ligand ULBP1, resulting in suppression of NK cell antitumor function." (PMID 34253709, 2021). "Together, our results showed that DOT1L is required for the growth of ovarian cancer cells and that its inhibition leads to the suppression of growth and tumor-forming characteristics in vitro." (PMID 34253709, 2021). "Taken together, our results demonstrate that DOT1L promotes ovarian cancer tumor growth and represents a new therapeutic target for ovarian cancer treatment." (PMID 34253709, 2021). "Results show ERα occupancy in HOXB3, TGM1, TWIST2, and WT1 gene promoters, which are all relevant for ovarian cancer, and DOT1L co-binding with ERα only in the TWIST2 and WT1 promoter regions." (PMID 31689915, 2019). "DOT1L is widely overexpressed in ovarian cancer and stimulates cell cycle progression via stimulating the CDK6 transcription." (PMID 31426393, 2019). "The expression of DOT1L can be regarded as an independent predictive factor and a potential area for therapeutic intervention in ovarian cancer." (PMID 30064416, 2018). "To identify genes regulated by DOT1L in ovarian cancer cells, we performed chromatin immune-precipitation coupled with high-throughput sequencing (ChIP-seq) analysis using ChIP-grade DOT1L antibody in SK-OV-3 cells." (PMID 28114995, 2017). "To identify the role of DOT1L in ovarian cancer, we performed immunohistochemistry and found that DOT1L expression was significantly increased in malignant ovarian cancer." (PMID 28114995, 2017). "DOT1L was an independent prognostic factor for the overall survival (OS) and progression-free survival (PFS) of ovarian cancer, and higher DOT1L expression was associated with poorer OS and PFS." (PMID 28114995, 2017). "To further determine the reason that knockdown DOT1L inhibits ovarian cancer cell proliferation, we next performed flow cytometric analysis of apoptosis and cell cycle." (PMID 28114995, 2017). "Taken together, these results suggest that DOT1L expression was significantly increased in malignant ovarian tumors." (PMID 28114995, 2017). "This suggests that DOT1L may be a valuable novel therapeutic agent against PARPi-resistant ovarian cancer." (PMID 38778348, 2024). "Inhibition of DOT1L combined with PARPi may have broad prospects in the clinical therapy of ovarian cancer." (PMID 38778348, 2024). "Indeed, studies suggest that Dot1l itself can serve as a prognostic biomarker for ovarian cancer and gastric cancer, and pharmacological inhibition of its activities with EPZ-5676 has a beneficial effect in patients with mixed lineage leukemia." (PMID 37397258, 2023). "ERα and DOT1L co-expression is an indicator of poor survival in ovarian cancer patients." (PMID 35873467, 2022).
ovarian carcinoma (continued). "The high expression of DOT1-like histone lysine methyltransferase (DOT1L) could promote ovarian cancer cell growth by regulating apoptotic and metabolic pathways, affecting patient prognosis." (PMID 35754835, 2022). "Moreover, compounds designed to repress DOT1L-mediated H3K79 methylation also showed efficacy in the treatment of ovarian cancer, further expanding the range of their potential applications for cancer therapy." (PMID 35495127, 2022). "Collectively, our results demonstrate that DOT1L promotes ovarian cancer tumor growth by regulating apoptotic and metabolic pathways as well as NK cell-mediated eradication of ovarian cancer and identifies DOT1L as a new pharmacological target for ovarian cancer therapy." (PMID 34253709, 2021). "In order to understand, whether the EPZ-5676-mediated growth inhibition of ovarian cancer cells growth is dependent on the expression levels of DOT1L and H3K79me2 chromatin mark, we measured their levels in a variety of ovarian cancer cells." (PMID 34253709, 2021). "DOT1L was also necessary for ovarian cancer tumor growth in both cell culture and in mice." (PMID 34253709, 2021). "In our study, we used the drug EPZ-5676 to determine if DOT1L is necessary for the growth of ovarian cancer cells and whether its inhibition can suppress their growth." (PMID 34253709, 2021). "Our results suggest that DOT1L might be a pharmacologically tractable drug target for ovarian cancer therapy." (PMID 34253709, 2021). "Because DOT1L is a chromatin modifier, we hypothesized that it promotes ovarian cancer growth by regulating gene expression." (PMID 34253709, 2021). "Finally, we find that DOT1L can suppress NK cell-mediated anti-ovarian cancer immunity, in part by repressing NK cell-activating ligands, such as ULBP1." (PMID 34253709, 2021). "The DOT1L upregulation in ovarian cancer cells might also contribute to drug resistance as it gets recruited onto the promoters of drug-resistant genes via transcriptional factor C/EBPβ." (PMID 31426393, 2019). "To determine whether DOT1L has a functional role in tumor progression in vivo, we used a mouse orthotopic xenograft ovarian cancer model." (PMID 28114995, 2017). "Consistent with previous finding that DOT1L siRNA-transfected human lung cancer cells undergo G1 cell cycle arrest, we showed here that knocking down of DOT1L in ovarian cancer cells could result in G1 arrest and therefore impede the cell proliferation." (PMID 28114995, 2017). "This study was designed to examine the expression of DOT1L (histone 3 lysine 79 methyltransferase) and H3K79 methylation in normal ovarian tissues and ovarian tumors and to explore the function of DOT1L and its underline mechanisms in ovarian cancer." (PMID 28114995, 2017). "Given that knocking down of DOT1L could inhibit the proliferation of ovarian cancer cells in vitro and induce G1 arrest we then proceeded to elucidate the molecular mechanism underlying this phenomenon." (PMID 28114995, 2017). "In order to evaluate the therapeutic effects of DOT1L inhibitors on a larger ovarian cancer cell line panel in vitro, we chose OV90 and CaOV3, which could represent high-grade serous ovarian cancer for CCK8 and colony formation assay." (PMID 28114995, 2017). "As expected, our in vitro experiment demonstrated that blocking DOT1L in ovarian cancer could lead to the decrease of ovarian cancer cell viability and colony-forming ability." (PMID 28114995, 2017). "Our results suggest that DOT1L might be potential target for prognostic assessment and therapeutic intervention in ovarian cancer." (PMID 28114995, 2017). "However, the role of DOT1L in the development of PARPi resistance in ovarian cancer remains unclear." (PMID 38778348, 2024).
ovarian carcinoma (continued). "Interestingly, high DOT1L expression has been shown to represent a biomarker of poor prognosis also in other gynecological malignancies, in particular ovarian cancer, where the expression of DOT1L has been associated with chemoresistance and shorter relapse-free (RFS) and overall (OS) survival." (PMID 35495127, 2022). "Thus, DOT1L plays important roles in the regulation of ovarian cancer tumor growth and progression." (PMID 34253709, 2021). "Additionally, similar results were obtained in DOT1L shRNA expressing ovarian cancer cells." (PMID 34253709, 2021). "To determine if the regulation of proapoptotic genes by DOT1L is clinically relevant, we checked whether the proapoptotic genes that were upregulated as a result of EPZ-5676 treatment in the ovarian cancer cell lines were repressed in ovarian tumor samples in which DOT1L was overexpressed." (PMID 34253709, 2021). "Importantly, DOT1L expression was identified as an independent prognostic factor for OC, which raised the possibility that DOT1L might be correlated with malignant behavior of ovarian cancer." (PMID 28114995, 2017). "Similar effects on ovarian cancer tumor growth in vivo in the xenograft model were observed with the administration of other DOT1L inhibitors, EPZ004777 and DOT1L shRNA." (PMID 34253709, 2021). "We showed that the DOT1L inhibitors (EPZ-5676, EPZ004777, and SGC0946) reduces the H3K79me2 mark and inhibit the growth of multiple ovarian cancer cell lines." (PMID 34253709, 2021). "Analysis of patient-derived samples of ovarian cancer showed that the intensity and quantity of ULBP1 expression were lower in samples with high DOT1L expression than in samples with low DOT1L expression." (PMID 34253709, 2021). "DOT1L inhibition also resulted in the upregulation of the NKG2D ligand ULBP1 and subsequent increase in natural killer (NK) cell-mediated ovarian cancer eradication." (PMID 34253709, 2021). "Here, the authors demonstrate that C/EBPβ and DOT1L together increase methylation of H3K79, which upregulates expression of oncogenic genes and drives poor platinum response and poor survival in ovarian cancer." (PMID 29712898, 2018). "We found that SGC0946 and EPZ004777 inhibited expression of DOT1L-targeted genes (MEIS1 and NANOG) in a dose-dependent manner, a finding which confirms the inhibitory effect of DOT1L activity in ovarian cancer cells." (PMID 29712898, 2018). "Consequently, DOT1L could have strong prospects for therapeutic target in ovarian cancer." (PMID 28114995, 2017). "Pharmacological inhibition of DOT1L additionally upregulates the expression of natural killer group 2 D (NKG2D) ligands, in particular ULBP1, which correlates with increased natural killer (NK) cell-mediated eradication of ovarian cancer cells." (PMID 34253709, 2021). "Pharmacological inhibition of DOT1L (EPZ-5676, EPZ004777, and SGC0946) or genetic inhibition of DOT1L attenuates the growth of ovarian cancer cells in cell culture and in a mouse xenograft model of ovarian cancer." (PMID 34253709, 2021). "In addition, H3K79 methylation was also significantly increased in malignant ovarian cancer, indicating the correlation of DOT1L and H3K79 methylation in ovarian cancer." (PMID 28114995, 2017). "This is the first study to examine DOT1L expression and H3K79 methylation in ovarian cancer." (PMID 28114995, 2017). "Immunohistochemical staining for DOT1L and H3K79 methylation expression was performed on 24 normal ovarian tissues, 15 benign ovarian tumors, 7 borderline ovarian tumors, and 228 malignant ovarian tumors." (PMID 28114995, 2017).
colorectal cancer (19 papers, 2010 to 2025). A primary or metastatic malignant neoplasm that affects the colon or rectum. "In colorectal cancer tissues, high DOT1L expression and H3K79me2 levels were associated with poor patient survival." (PMID 31888761, 2019). "DOT1L encodes a histone methyltransferase acting at lysine-79 of histone H3 which was recently been shown to be an activator in colorectal cancer and functions in DNA repair in yeast." (PMID 25261372, 2014). "Still, Dot1l has been reported to have association with other cancers, such as colorectal cancer." (PMID 27713173, 2016). "CBP-mediated DOT1L K358 acetylation promotes colorectal cancer metastasis by preventing DOT1L (an enzyme that catalyzes H3K79 methylation) from proteasomal degradation without affecting its enzyme activity." (PMID 35053509, 2022). "We also detected the DOT1L protein and DOT1L mRNA levels in human colorectal carcinomas and their paired adjacent normal tissues." (PMID 32042335, 2020). "We found that DOT1L was highly expressed in colorectal cancer and was negatively related to the prognosis of patients with CRC." (PMID 31888761, 2019). "The link between a higher DOT1L expression and a worst patient’s prognosis has been confirmed also in other malignancies of the gastrointestinal tract, such as in colorectal cancer (CRC), where a positive correlation between DOT1L and MYC expression was found in several cohorts of CRC patients." (PMID 35495127, 2022). "Here, we aimed to identify specific DOT1L post-translational modifications that might regulate DOT1L activity and thus impact on colorectal cancer (CRC) progression." (PMID 32042335, 2020). "DOT1L is a potential marker for colorectal cancer and EPZ004777 may be a potential drug for the treatment of colorectal cancer." (PMID 31888761, 2019). "Our results provided an example of the relationship between histone methylation in colorectal cancer and DOT1L might be a potential therapeutic target for CRC treatment." (PMID 31888761, 2019). "Importantly, we show that small molecule inhibitors of DOT1L combined with chemotherapeutic agents that are used to treat colorectal cancers show additive effects." (PMID 30616689, 2019). "Interestingly, high level of DOT1L expression and H3K79me2 was a predictor of poor patient survival of colorectal cancer." (PMID 29796335, 2017). "Due to its role in development, it is not surprising to find that DOT1L is linked to many human diseases, including prostate cancer, colorectal cancer, and hypertension." (PMID 29796335, 2017). "The methyltransferase DOT1L may present an attractive candidate for drug targeting in colorectal cancer." (PMID 21103407, 2010). "We conclude that the enzyme Dot1l may present an attractive candidate for drug targeting in colorectal cancer." (PMID 21103407, 2010). "Other studies found that Dot1l epigenetically promoted the transcription of c-Myc via H3K79me2, while silence or inhibition of Dot1l induced cell cycle arrest in colorectal cancer cells, suggesting that Dot1l inhibitor might be a potential drug for the treatment of colorectal cancer." (PMID 33628364, 2021). "Thus, we hypothesized that DOT1L-mediated H3K79me3 levels may correlate with patient outcome in colorectal cancer." (PMID 30616689, 2019). "In this study, we aimed to explore the function of DOT1L, the effect of EPZ004777 and its molecular mechanism in colorectal cancer." (PMID 31888761, 2019). "Intriguingly, DOT1L expression in COAD was higher than that of READ, and was highly expressed in colorectal carcinoma than that of colorectal adenoma." (PMID 31888761, 2019). "Depletion of MLLT10/AF10 in colorectal cancer and Wnt-inducible HEK293T cells followed by expression array analysis identifies MLLT10/AF10 and DOT1L as essential activators to a large extent dedicated to Wnt target gene regulation." (PMID 21103407, 2010).
colorectal cancer (continued). "In this study, we examined the role of DOT1L in DNA double-strand break (DSB) response and repair by depleting DOT1L using siRNA or inhibiting its methyltransferase activity using small molecule inhibitors in colorectal cancer cells." (PMID 30616689, 2019).